DUOXA1 (dual oxidase maturation factor 1)
Description:
Required for the maturation and transport of functional DUOX1 from the endoplasmic reticulum to the plasma membrane. Recruits DUOX1 to the apical cell membrane.
Synonyms: NIP; NUMBIP; FLJ32334; mol
Tractability: Small molecule: a structure with a bound ligand is known. Antibody: its Gene Ontology location is reachable by antibodies, with high confidence; UniProt predicts a signal peptide or a membrane-spanning region.
Gene: Protein-coding gene on chromosome 15 (45,117,364 to 45,130,611, reverse strand). Ensembl gene ENSG00000140254.
Subcellular location: Apical cell membrane
Pathways (Reactome):
Metabolism: Thyroxine biosynthesis
Gene Ontology:
Molecular function: protein binding
Biological process: hydrogen peroxide biosynthetic process; intracellular protein localization; positive regulation of hydrogen peroxide biosynthetic process; protein localization to plasma membrane; regulation of thyroid hormone generation; protein transport
Cellular component: apical plasma membrane; NADPH oxidase complex; membrane; plasma membrane; endoplasmic reticulum membrane
Genetic constraint (gnomAD): Loss-of-function variants: 20 observed, 28.71 expected, observed/expected ratio (o/e) 0.7, 90% interval 0.49 to 1.01. The upper end of that interval is the gene's LOEUF score, 1.01, which puts it in group 4 of 6, group 1 being the genes least tolerant of losing a copy. Missense variants: 403 observed, 445.72 expected, observed/expected ratio (o/e) 0.9, 90% interval 0.83 to 0.98. Synonymous variants: 166 observed, 185.57 expected, observed/expected ratio (o/e) 0.89, 90% interval 0.79 to 1.02.
Homologues: Orthologues: macaque DUOXA1 (95% identical), chimpanzee DUOXA1 (84% identical), mouse Duoxa1 (83% identical), pig DUOXA1 (83% identical), rat Duoxa1 (81% identical), dog DUOXA1 (74% identical), rabbit DUOXA1 (68% identical), tropical clawed frog duoxa1 (42% identical), Caenorhabditis elegans doxa-1 (35% identical), zebrafish duox2 (33% identical), Drosophila melanogaster mol (32% identical). Paralogues in human: DUOXA2 (50% identical).
Diseases named in the same sentence as DUOXA1 in open-access papers:
DUOXA1 is named in the same sentence as 23 diseases in open-access papers, as found by Europe PMC text mining. Sharing a sentence is not in itself a finding about the gene and the disease. The quoted sentences say what the papers report.
breast carcinoma (3 papers, 2013 to 2021). "Duoxa1, which was originally identified as a numb-interacting protein, was recently shown to function as a maturation factor in breast cancer." (PMID 23555558, 2013). "Moreover, DUOX1 silencing in lung epithelial and cancer cell lines was associated to epithelial-to-mesenchymal transition, which is linked to metastasis, and transient overexpression of DUOXA1, a maturation factor of DUOX1, in breast cancer cells affected cell-cell adhesion." (PMID 29849884, 2018). "Other genes were associated with cell adhesion and migration of breast cancer cell [DUOXA1 and PGAM1], prognosis of breast cancer [PGK1 and KLK10], or clinical outcome in breast cancer [RBM3 and AQP5]." (PMID 34497807, 2021).
hypothyroidism (3 papers, 2019 to 2022). Abnormally low levels of thyroid hormone. "Genes related to TH biogenesis show a normal response to TSH stimulation in hypothyroidism, including Tpo, Pendrin, Tshr, Nis, Mct8, Duox1, Duox2, Duoxa1, and Duoxa2." (PMID 35326426, 2022).
lung carcinoma (3 papers, 2016 to 2021). "Recent evidence has indicated that DUOX1 and DUOXA1 were frequently silenced due to promoter hypermethylation in various epithelial cancers including lung cancer." (PMID 34026765, 2021). "Lung cancer also presents decreased expression of DUOX1 and DUOX2 that iscorrelated with hypermethylation of CpG-rich promoter regions of DUOX genes.Moreover, DUOXA1 and DUOXA2 weredown-regulated in lung cancer cells and lung cancer tissues." (PMID 32453337, 2020). "Similar reversal of EMT features were observed after overexpression of DUOX1, but not DUOXA1, in the metastatic lung cancer cell line NCI-H187 in which DUOX1 is also silenced." (PMID 27694834, 2016).
congenital hypothyroidism (2 papers, 2019 to 2023). A thyroid hormone deficiency present from birth. "Ultimately, the crucial role of DUOX1 in human thyroid function was demonstrated in patients with congenital hypothyroidism (CH): two heterozygous missense mutations in DUOX1 and DUOXA1 in two patients can cause CH through disrupting the coordination of DUOX1 and DUOXA1 in the generation of H2O2." (PMID 36835420, 2023). "DUOX2/DUOXA2 defects can cause congenital hypothyroidism (CH), but it is unknown whether DUOX1/DUOXA1 mutations can also cause CH." (PMID 31428054, 2019).
goiter (2 papers, 2019 to 2020). Enlargement of the thyroid gland usually caused by lack of iodine in the diet, hyperthyroidism, or thyroid nodules. "Patients and Methods: Forty-three children with CH with goiter were enrolled, in whom all exons and flanking intronic regions of DUOX1/DUOXA1 were directly sequenced." (PMID 31428054, 2019).
atherosclerosis (1 paper, 2023). A disease characterized by the build-up of fatty material and calcium deposition in the arterial wall resulting in partial or complete occlusion of the arterial lumen. "Moreover, the oxygen radicals produced by DUOXA1 are associated with intravascular plaque formation, which is a critical risk factor for atherosclerosis." (PMID 37033267, 2023).
Crohn disease (1 paper, 2024). A gastrointestinal disorder characterized by chronic inflammation involving all layers of the intestinal wall, noncaseating granulomas affecting the intestinal wall and regional lymph nodes, and transmural fibrosis. "Since Crohn’s disease and ulcerative colitis both belong to inflammatory bowel diseases, DUOXA1 has potential research value." (PMID 38343536, 2024). "In our exploration of the expression of angiogenesis-related genes in Crohn’s disease patients, we found upregulation of OSM, CXCL5, CEACAM3, ISG20, and DUOXA1 genes in Crohn’s disease patients." (PMID 38343536, 2024).
embryonal carcinoma (1 paper, 2018). A non-seminomatous malignant germ cell tumor characterized by the presence of large germ cells with abundant cytoplasm resembling epithelial cells, geographic necrosis, high mitotic activity, and pseudoglandular and pseudopapillary structures formation.
metabolic syndrome (1 paper, 2023). A cluster of metabolic risk factors for CARDIOVASCULAR DISEASES and TYPE 2 DIABETES MELLITUS. "Seven metabolic syndrome-related genes (CSF3R, TMEM132A, STAB1, VIM, DUOXA1, PILRB, and SLC2A4) were used to construct risk equations." (PMID 37033267, 2023).
osteoporosis (1 paper, 2020). A condition of reduced bone mass, with decreased cortical thickness and a decrease in the number and size of the trabeculae of cancellous bone (but normal chemical composition), resulting in increased fracture incidence. "In conclusion, these findings highlight the crucial role of ROS generation by Duoxa1 in osteoclast differentiation and reveal Duoxa1 as a potential therapeutic target in treating bone diseases associated with excess osteoclasts-induced bone loss such as osteoporosis and Paget’s disease of bone." (PMID 32899248, 2020).
cancer (4 papers, 2013 to 2022). A tumor composed of atypical neoplastic, often pleomorphic cells that invade other tissues. "Moreover, its interaction with DUOX1 and DUOXA1 emphasized similar contributions to inhibit the malignant progress of cancer." (PMID 34026765, 2021). "Consistent with pan-cancer analysis, DUOX1 and DUOXA1 were also downregulated in LUAD from our TCGA dataset, proving their potential tumor suppression roles." (PMID 34026765, 2021).
infection (4 papers, 2014 to 2025). The state of being infected such as from the introduction of a foreign agent such as serum, vaccine, antigenic substance or organism. "Quantitative RT-PCR indicated that DUOXA1 overexpressing samples had significantly elevated levels of ASK1 mRNA by five hours post infection (P < 0.05)." (PMID 24410844, 2014). "It is noteworthy that within our cohort, 26 patients with additional infections carried damaging variants in CLEC7A, PLCG2, or DUOX1/DUOXA1, compared with 6 of 27 patients without additional serious infections (n = 26 of 40 vs. 6 of 27; P = 0.001)." (PMID 36166305, 2022). "Taken together, these data suggest variants in the CLEC7A/PLCG2/DUOX1/DUOXA1 pathway are not risk factors for primary infection but rather for control of infection (CLEC7A) and dissemination (PLCG2/DUOX1/DUOXA1)." (PMID 36166305, 2022). "In the aggregate, these studies suggest that variants in the CLEC7A/PLCG2/DUOX1/DUOXA1 pathway are not risk factors for primary infection but rather for control of infection (CLEC7A) and dissemination (PLCG2/DUOX1/DUOXA1)." (PMID 37233265, 2023).
DUOXA1 also shares sentences with these, for which no sentence is quoted: tumor (3 papers); chronic granulomatous disease (1); Coccidioides infection (1); E. coli infection (1); inflammatory bowel disease (1); Obesity (1); ovarian carcinoma (1); Paget’s disease of bone (1); thyroid dysgenesis (1); thyroid dyshormonogenesis (1); ulcerative colitis (1).